DECR1 (2,4-dienoyl-CoA reductase 1)
Diseases named in the same sentence as DECR1 in open-access papers (continued):
Sharing a sentence is not in itself a finding about the gene and the disease.
tumor (25 papers, 2012 to 2026). "Raman spectroscopy was performed on the tumour slides to test if loss of DECR1 expression perturbed intra-tumoural contents of lipids and cholesterol-based compounds." (PMID 32427840, 2020). "Mechanistically, a large number of biomolecules and tumor-associated signaling pathways, including DECR1, PANX2, HSPB1, ACOT8, SUV39H1, NCOA4, PI3K-AKT-mTOR signaling, VHL/HIF-2α pathway, and Hippo/TAZ signaling pathway, have been reported to regulate ferroptosis in urologic cancers." (PMID 34922551, 2021). "Raman spectra obtained for DECR1 KO tumours demonstrated reduced intensity of bands at 2845 cm−1 (lipids) and 2880 cm−1 (cholesterol), suggesting that DECR1-deficient tumours had reduced levels of lipid and cholesterol compounds in comparison to control tumours." (PMID 32427840, 2020). "2,4-dienoyl coenzyme A reductase (DECR1), a beta-oxidation coenzyme, is a clinically relevant biomarker for CRPC, and DECR1 deficiency impairs lipid metabolism and reduces CRPC tumor growth." (PMID 36324578, 2022). "Deletion of DECR1 can impair lipid metabolism and reduce tumor growth; therefore, DECR1 is important in the progression of tumor growth and treatment resistance." (PMID 36131793, 2022). "Silencing of DECR1 impaired tumour growth in castrated mice, significantly reducing tumour volume by an average of 41% (assessed by ultrasonography)." (PMID 32427840, 2020). "DECR1 KO tumours presented a pronounced decrease in several highly abundant triglycerides species, which accounted for a large proportion of total lipid content." (PMID 32427840, 2020). "In contrast to our data, DECR1 was proposed to act as a tumour suppressor in HER2-positive breast cancer." (PMID 32427840, 2020). "Further study revealed that the expression of DECR1 was required for growth of CRPC tumor in vivo." (PMID 35756667, 2022). "DECR1 knockdown selectively inhibited β-oxidation of PUFAs, inhibited proliferation and migration of PCa cells, including treatment resistant lines, and suppressed tumor cell proliferation and metastasis in mouse xenograft models." (PMID 32686647, 2020). "As DECR1 is a directly androgen-repressed gene, its expression increases after castration or treatment with anti-androgens and is hypothesized to maintain tumor cell survival under castration conditions." (PMID 32686647, 2020). "Moreover, similar to what is observed in vitro, DECR1 KO tumours showed an increase in several ceramides and multiple polyunsaturated phospholipids." (PMID 32427840, 2020). "Furthermore, DECR1 KO tumours were highly necrotic and displayed a lower level of cellularity than the control tumours." (PMID 32427840, 2020). "Therefore, we examined the impact of reduced DECR1 expression on the growth of CRPC tumours in vivo." (PMID 32427840, 2020). "Subsequently, the differential analysis of DECR1 expression in normal and tumors in the TCGA-LUAD database showed that the expression of DECR1 was higher in tumor samples than in normal samples." (PMID 41169393, 2025). "DECR1 deletion in vivo, on the other hand, inhibited lipid metabolism, and reduced CRPC tumor growth." (PMID 35736421, 2022). "Mechanistically, blocking enzymes such as DECR1, PANX2 and GPX4 can inhibit tumor growth with universal implications in understanding both resistance and metabolic events." (PMID 33596934, 2021). "Downregulation of proteins involved in the mitochondrial respiratory chain like NFU1, ACO2, PDHA1, and proteins like DECR1, CNDP2, and SPINT1, which have a tumor suppressive role in different cancers were noted." (PMID 34885041, 2021). "In vivo, DECR1 deletion impairs lipid metabolism and reduces CRPC tumour growth, emphasizing the importance of DECR1 in the development of treatment resistance." (PMID 32427840, 2020). "(D) qRT-PCR analysis of DECR1 and androgen regulated genes KLK2 and KLK3 mRNA expression in a cohort of 10 patient-derived human prostatic ex vivo tumor explants treated with enzalutamide (ENZ, 10 μM)." (PMID 32686647, 2020).
tumor (continued). "Short term ARI treatment or androgen withdrawal induced DECR1 expression in prostate cell lines, while long-term ADT treatment in patients and tumour-bearing mice resulted in strong upregulation of the protein." (PMID 32427840, 2020). "2,4-dienoyl-coA reductase (DECR1) knockout → induced ER stress, and stimulated CRPC cells to undergo ferroptosis.DECR1 deletion in vivo → inhibited lipid metabolism, and reduced CRPC tumor growth." (PMID 35736421, 2022). "In vivo, DECR1 knockout attenuates lipid metabolism and reduces CRPC tumor growth." (PMID 35053570, 2022). "DECR1 deletion in CRPC cells reduces in vitro proliferation and impairs CRPC tumour growth." (PMID 32427840, 2020).
cancer (13 papers, 2012 to 2026). A tumor composed of atypical neoplastic, often pleomorphic cells that invade other tissues. "We observed overexpression of DECR1 in PCa tissues (n = 8) compared with benign tissues (n = 3), and increased expression was evident in high grade versus low grade cancer tissue." (PMID 32686647, 2020). "Expression change of DECR1; the auxiliary enzyme in β-oxidation of fatty acids is reported in several cancers." (PMID 29511485, 2017). "However, in the same study, DECR1 overexpression was also shown to protect cancer cells from glucose withdrawal-induced apoptosis." (PMID 32427840, 2020). "Taken together, these results suggest that DECR1 may contribute to increase metabolic flexibility of cancer cells under stress conditions, and uncover an unexpected link between DECR1 function and ER homeostasis." (PMID 32427840, 2020). "Interestingly, the top three cancer types exhibiting increased DECR1 copy gain were hormone-dependent tumors (uterine, breast and prostate), suggestive of a relationship between DECR1 expression and hormone signaling." (PMID 32686647, 2020). "Surprisingly, very little is known about the biological role of DECR1 in cancer." (PMID 32686647, 2020). "Therefore, by regulating lipid saturation level, DECR1 might act in several ways to support cancer cell survival." (PMID 32427840, 2020). "DECR1 expression was markedly increased in a panel of hormone-dependent and -independent cancer cell lines compared with non-malignant PNT1 and PNT2 prostate cell lines." (PMID 32686647, 2020). "To date, the role of DECR1 in cancer has not been well-studied." (PMID 32427840, 2020). "Additionally, TCGA pan-cancer data revealed a negative correlation between METTL3 and DECR1 expression in LIHC." (PMID 39629121, 2024).
DECR1 also shares sentences with these, for which no sentence is quoted: endothelial dysfunction (6 papers); chronic granulomatous disease (5); atherosclerosis (4); Hypertension (3); acute pancreatitis (2); cardiomyopathy (2); cardiovascular disease (2); Cirrhosis (2); diabetic nephropathy (2); gastric cancer (2); Hepatic steatosis (2); infection (2); melanoma (2); metastatic disease (2); psoriasis (2); renal disease (2); acute kidney injury (1); Anxiety (1); asthma (1); bacterial infection (1); CHILD syndrome (1); chronic gastritis (1); chronic kidney disease (1); Crohn disease (1); deficiencies (1); depression (1); developmental delay (1); Encephalopathy (1); energy metabolism disorder (1); esophageal SCC (1).
A further 14 diseases each share a sentence with DECR1 in 1 paper.